TRIM6-TRIM34 (TRIM6-TRIM34 readthrough)
Gene: Protein-coding gene on chromosome 11 (5,596,725 to 5,644,398, forward strand). Ensembl gene ENSG00000258588.
Genetic constraint (gnomAD): Loss-of-function variants: 82 observed, 87.56 expected, observed/expected ratio (o/e) 0.94, 90% interval 0.78 to 1.12. The upper end of that interval is the gene's LOEUF score, 1.12, which puts it in group 4 of 6, group 1 being the genes least tolerant of losing a copy. Missense variants: 1,004 observed, 1,013.7 expected, observed/expected ratio (o/e) 0.99, 90% interval 0.94 to 1.04. Synonymous variants: 335 observed, 369.42 expected, observed/expected ratio (o/e) 0.91, 90% interval 0.83 to 0.99.